GAL (galanin and GMAP prepropeptide)
Diseases named in the same sentence as GAL in open-access papers (continued):
Sharing a sentence is not in itself a finding about the gene and the disease.
spinal cord injury (1 paper, 2021). Penetrating and non-penetrating injuries to the spinal cord resulting from traumatic external forces (e.g., WOUNDS, GUNSHOT; WHIPLASH INJURIES; etc.). "It has been suggested that upregulation of GAL expression in DRG neurons in micturition pathways after spinal cord injury (SCI) may be mediated by changing neurotrophic factors expression such as NGF and brain-derived neurotrophic factor (BDNF)." (PMID 34948196, 2021).
thyrotroph adenomas (1 paper, 2022). "Another study has shown that the synthesis of GAL was inhibited in thyrotroph adenomas." (PMID 35954419, 2022). "The GAL gene expression was blocked in thyrotroph adenomas; these inhibitory mechanisms must be studied in-depth, since they could be useful to develop antitumor strategies." (PMID 35954419, 2022). "The expression of the GAL gene was blocked in thyrotroph adenomas; this means that GAL did not exert a stimulatory proliferative action on thyrotrophs." (PMID 35954419, 2022).
tongue cancer (1 paper, 2025). A malignant neoplasm affecting the tongue. "The findings revealed that, in comparison to their levels in normal tissues, the genes GAL, GHRH, LCE2B, PCDHGC5, and MT3 were notably upregulated in tongue cancer, while NTS was downregulated." (PMID 40255484, 2025).
toxicity (1 paper, 2025). The degree to which an agent can damage an organism. "GAL and SCOP show the highest scores for hepatotoxicity, whereas rutin has an increased risk of drug-induced liver toxicity (0.937) and genotoxicity (0.868)." (PMID 40430525, 2025).
virus infection (1 paper, 2022). "Protein kinase A (PKA) and protein kinase C (PKC) are inducers of the expression of the GAL gene, and the expression and release of GAL is promoted by axotomy, chronic stress, ischemic brain damage, orofacial pain, virus infection and chronic constriction nerve injury." (PMID 35954419, 2022).
tumor (38 papers, 1995 to 2025). "The presence of GALRs on tumor-associated immune cells, especially macrophages, indicates that GAL signaling contributes to homeostasis of the tumor microenvironment." (PMID 32265844, 2020). "Although, GAL is expressed in several malignant tumors and is associated with cell proliferation and tumor growth, the prognostic value of GAL expression in cancer patients is not completely understood." (PMID 25504183, 2015). "Although galanin (GAL) is expressed in several malignant tumors and is associated with cell proliferation and tumor growth, the prognostic value of GAL expression in CRC is poorly understood." (PMID 25504183, 2015). "Our data showed that high expression of GAL was significantly associated with tumor relapse and poor prognosis of CRC patients." (PMID 25504183, 2015). "Higher expression of GAL was associated with tumor recurrence among the CRC patients (P<0.001)." (PMID 25504183, 2015). "Thus, the subpopulation of CRC cells that sustain high GAL expression may be more aggressive and have the potential to cause tumor recurrence in CRC patients." (PMID 25504183, 2015). "The in vivo dynamic study of GAL-MPA in tumor-bearing mice (HepG2, MCF-7, A549, HCT116, U87, MDA-MB-231, and S180) showed its high tumor-targeted ability with the maximal tumor/normal tissue ratio up to 6.8." (PMID 38543094, 2024). "The fluorescence probe GAL-MPA displayed higher cell affinity to tumor cells (HepG2, MCF-7, and A549) than to normal liver cells L02 in vitro." (PMID 38543094, 2024). "In the present study, we found a trend towards an inverse correlation of GAL expression in the cholangiocytes of pCCA with tumour grading." (PMID 37443714, 2023). "Cases were divided into those with high and low expression of GAL or GAL1–3-R tumour cells, respectively." (PMID 37443714, 2023). "SSTR1 hypermethylation has been detected in 64% of HNSCC samples and has also been associated with tumor extent, disease stage, SST hypermethylation, and increased expression of galanin (GAL), GALR2, TAC1, and tachykinin type 1 receptor (TACR1)." (PMID 36769317, 2023). "In conclusion, our findings demonstrated that the GAL/GALR2 axis promoted SACC‐PNI via modulating tumor cell EMT." (PMID 36039037, 2023). "This is supported by the finding that GAL expression tended to inversely correlate with tumour grading." (PMID 37443714, 2023). "In vitro nerve‐tumor co‐culture results showed that GAL increased the expression of N‐cadherin and Vimentin (mesenchymal biomarkers) while suppressing the expression of E‐cadherin (epithelial biomarker) in SACC cells." (PMID 36039037, 2023). "Different from other peptidergic systems, the galaninergic system exerts a proliferative action on tumor cells, but GAL also suppresses the development of tumors." (PMID 35954419, 2022). "Second, the detailed mechanism between GAL expression and tumor immune CD8+ T cells is still unclear." (PMID 35751103, 2022). "In CRC patients, a high GAL expression was related to tumor recurrence, and CRC patients (stage II) who showed a high GAL expression had a poorer prognosis than those showing a low expression of the peptide." (PMID 35954419, 2022). "GAL (released from nerves) exerted a nerve–tumor crosstalk by activating GAL2R expressed in tumor cells and by inducing NFATC2-mediated transcription of cyclooxygenase-2 and GAL; then, GAL released from tumor cells promoted neuritogenesis, favoring PNI." (PMID 35954419, 2022). "In neuroblastic tumors, a low level of GAL binding sites has been correlated with survival and GAL/GALR expressions have been related to tumor differentiation stages." (PMID 35954419, 2022). "The expression of GALRs in tumor-related immune cells suggests that GAL regulates the homeostasis of the tumor microenvironment." (PMID 35954419, 2022).
tumor (continued). "Although our previous studies demonstrated high galanin (GAL) presence within tumor tissue and an elevated concentration of GAL in the serum of CRC patients, to date, there is a lack of data regarding GAL receptor (GalR) protein expression in CRC cells." (PMID 35409094, 2022). "It is worth noting that many genes were dramatically upregulated specifically in ACTH+&CRH + pheochromocyte when compared with the other tumor cell types, such as GAL, POMC, PNMT, and CARTPT." (PMID 34905486, 2021). "In a human study, GAL expression at the mRNA level was up-regulated in the tumour tissue and correlated with poor prognosis and tumour recurrence in CRC patients in stage II of the disease." (PMID 32403316, 2020). "GAL protein was stained on the cell membrane and cytoplasm in tumor tissues, and MMP3 protein was stained on the cell cytoplasm in tumor tissues." (PMID 31793228, 2020). "In the present study, in the cancer-affected stomach wall, the density of nerve fibers in the muscle layers immunoreactive to CART and/or GAL was clearly changed in proximity to tumor invasion, when compared to the unchanged area." (PMID 30373200, 2018). "Immunofluorescent staining showed that the percentages of PGP9.5+ neurons expressing CART and/or GAL were similar in both studied regions: close to tumor invasion and in the region distal from it." (PMID 30373200, 2018). "In case of this peptide, it has only been reported that in the group of patients with CRC, the percentage of the neurons containing GAL was similar in the MPs located close to and distally from tumor invasion." (PMID 30019295, 2018). "Present results demonstrate that the percentage of neurons containing GAL located distally from the tumor invasion was higher, while containing CASP-3 was lower when compared to cancer-affected region." (PMID 30019295, 2018). "The current findings provide novel direct epigenetic evidence for the involvement of SST, TAC1, hypocretin neuropeptide precursor (HCRT), neuropeptide Y (NPY), and GAL in the process of tumor suppression in humans." (PMID 29682090, 2018). "In the present study, we conducted a retrospective study to analyze GAL expression in stage II CRCs and stage III CRCs and to examine GAL expression as an indicator of tumor recurrence of CRC patients." (PMID 25504183, 2015). "Consistent with the in vitro findings, the tumor formation and growth rates of both Galanin (GAL) and GALR1 expressing HNSCC cells are significantly reduced in vitro." (PMID 26251921, 2015). "Given the tissue-specific expression patterns of lncRNAs demonstrated in the study, targeting GAL in GBM may offer a selective strategy to suppress GLUT1 expression in tumor cells." (PMID 40563757, 2025). "Moreover, GAL expression showed a trend of inverse correlation with tumour grading, with high GAL expression in differentiated Grade 1 tumours and consecutively declining GAL expression with tumour dedifferentiation." (PMID 37443714, 2023). "GAL and GAL-Rs play diverse roles in tumour development and proliferation." (PMID 37443714, 2023). "Furthermore, GAL and its receptors are expressed in various tumours and can modify tumour activity depending on the tumour type, as well as the type of receptor expressed." (PMID 37443714, 2023). "Many of the proliferative and antiproliferative actions mediated by GAL on tumor cells could be explained by the signal transduction pathways depending on the coupled G protein type." (PMID 35954419, 2022). "Some peptidergic systems (e.g., substance P/neurokinin-1 receptor system, neurotensinergic system) exclusively promote the proliferation of tumor cells; however, GAL, via different GALRs, exerts a tumor cell proliferative action, but also the peptide suppresses the development of tumors." (PMID 35954419, 2022). "In this study, GAL favored the extension of processes by dorsal root ganglion neurons, but the action of the peptide on tumor cells is currently unknown." (PMID 35954419, 2022).
tumor (continued). "However, only GAL was significantly correlated with tumor immune-infiltrating cells, especially CD8+ T cells." (PMID 35751103, 2022). "GAL may promote pituitary cell proliferation and tumor development in an estrogen-dependent or independent manner." (PMID 35954419, 2022). "Galanin (GAL) exerts both proliferative and antiproliferative actions in tumor cells." (PMID 35954419, 2022). "Human pheochromocytoma was the first tumor in which GAL was identified." (PMID 32265844, 2020). "Interestingly, we found that the number of neurons containing galanin (GAL) within myenteric plexuses located in the vicinity of the infiltrating cancer was higher compared to the MPs in a region distally located from the tumour margin." (PMID 32403316, 2020). "GAL protein stained positive in 58.9% (116/197) tumor tissues and 2.5% (5/197) normal tissues." (PMID 31793228, 2020). "In HNSCC, recent data are conflicting, with significant GAL overexpression reported in tumor samples, whereas our previous study proposed that GAL promoter methylation and gene silencing is correlated with significantly lower DFS and growth suppression of HNSCC cells after forced gene expression." (PMID 29682090, 2018). "Moreover, percentage of GAL-immunoreactive neurons devoid of CASP8 was significantly higher only in vicinity of tumor invasion." (PMID 30019295, 2018). "Therefore, we further examined the association between the survival of CRC patients and the status of GAL expression according to tumor stage." (PMID 25504183, 2015). "Finally, we defined the cellular pattern of GAL and its receptors in tumour cells of pCCA." (PMID 37443714, 2023). "In our study, tumour cells of pCCA demonstrated high GAL immunoreactivity, with similar mean expression in comparison to healthy cholangiocytes pCCA patients with available survival rates (n = 18) were divided into two groups; high GAL expressors and low GAL expressors." (PMID 37443714, 2023). "Consequently, low levels of GAL in tumour tissues could lead to enhanced vascularisation, which can still be seen in neighbouring benign tissue." (PMID 37443714, 2023). "Thus, GAL can promote or inhibit the development of tumors; this is an important characteristic of the galaninergic system: to exert both proliferative and antiproliferative actions on tumor cells." (PMID 35954419, 2022). "Finally, PGLYRP3, GAL, ADCYAP1R1 and LIF were selected to construct the Tumor Mutation Burden Immune Prognostic model (TMB-IP) using the following formula: TMB-IP score = (PGLYRP3*0.0988045135949462 + GAL*0.0483710471635067 + ADCYAP1R1*0.123387518699318 − LIF*0.121787959868336)." (PMID 33836680, 2021). "Additionally, it is unclear whether the secreted GAL originates from the tumor itself or from adjacent healthy tissue, for example, the pituitary which was shown to exhibit high GAL mRNA levels as well as medium to strong diffuse and focal GAL staining." (PMID 32265844, 2020). "Therefore, it could also be possible that GAL is secreted by the tumor cells showing focal GAL staining to boost tumor-supporting properties of the GAMs." (PMID 32265844, 2020). "Therefore, it could be possible that GAL also induces tumor-suppressing functions in GAL3-R positive GAMs." (PMID 32265844, 2020). "Thus, our data indicate that GAL signaling in tumor-supportive myeloid cells could be a novel therapeutic target." (PMID 32265844, 2020). "It should be underlined that changes in the neuronal subpopulations associated with CART and/or GAL availability could also impact on tumor growth without the influence on its grading." (PMID 30373200, 2018). "Thus, the significance of GAL expression for tumor proliferation and invasion may differ according to stage." (PMID 25504183, 2015). "This argument is supported by the fact that GAL, VIP and SP are involved in neuroprotective reactions that occur in response to various pathological factors, such as inflammation, neoplasm or intoxication." (PMID 36982030, 2023).
tumor (continued). "Low concentrations of GAL, somatostatin and serotonin have been reported in CRC patients and treatment with GAL alone showed an important decrease in the number of tumor blood vessels." (PMID 35954419, 2022). "The GAL-mediated Akt pathway blocked the activity of caspases 3 and 9, whereas the GAL2R-mediated apoptosis in tumor cells was induced by the activation of the pro-apoptotic Bcl-2 protein Bim, through a mechanism independent of caspase." (PMID 35954419, 2022). "In fact, GAL promoted CRC cell proliferation and improved cell survival, and then cancer cell invasiveness increased and tumor development was accelerated." (PMID 35954419, 2022). "To validate this finding, we performed additional IHC staining experiments on paraffin-embedded serial slices with similar tissue regions from the tumor specimen esPHEO_T3 using antibodies against CgA, ACTH, POMC, CRH, TH, and GAL." (PMID 34905486, 2021). "C3, APP, GAL, and C3AR1 have also been shown to be involved in the regulation of cancer cell metastasis and tumor invasion in multiple cancers." (PMID 34239596, 2021). "Three genes were selected, namely, ANO1, GAL, and MMP3, which were aberrantly expressed in ESCC tumor tissues (P < .001)." (PMID 31793228, 2020). "The positive expression rates of ANO1, GAL, and MMP3 in ESCC tumor tissues were significantly higher compared to those in normal tissues (all P at <.001)." (PMID 31793228, 2020). "The evaluation of GAL‐9 (GAL‐9A) in the primary tumor did not demonstrate statistically significant differences between R and C patients, but numerical differences were seen." (PMID 36751105, 2023). "The data show that the expression of GAL is related to CRC aggressive behavior and it seems that CRC cells showing a high GAL expression are more malignant and are also involved in the recurrence of the tumor." (PMID 35954419, 2022). "The number of neurons containing GAL also increased in the tissue regions located close to CRC; thus, the release of GAL from these neurons could block apoptotic mechanisms favoring tumor cell survival and proliferation." (PMID 35954419, 2022). "Other studies of GAL and its receptors also suggest the role of GAL as a cancer-promoting factor in non-CRC neoplasms." (PMID 32403316, 2020). "Recent studies claim that GAL and GALR2 play a significant role in nerve-tumor interactions." (PMID 29854027, 2018). "However, the role of the GAL system in cancer is still not entirely elucidated, as there is evidence for this system serving both tumour promotor and suppressor functions." (PMID 37443714, 2023). "In addition, we are not aware of any study reporting the expression of the GAL system, especially GAL3-R, in tumor-associated neutrophilic granulocytes." (PMID 32265844, 2020). "Thus, GAL is antiproliferative by GALR1 and stimulates aggressive tumor growth by GAL2." (PMID 29854027, 2018). "We compared GAL expression between 56 patients with stage II and III CRC who developed tumor recurrences and 56 patients who did not." (PMID 25504183, 2015). "Quantitative real-time PCR revealed significantly higher expression of GAL in CRC with tumor recurrence compared with CRC without tumor recurrence (P<0.001) and the GAL expression level was higher in stage II CRCs than in stage III CRCs (P<0.001)." (PMID 25504183, 2015). "Additionally, it should be underlined that the results of the present study indicate that although tumor invasion had no influence on the number of PGP 9.5+ nerve fibers in the LML, it had a large impact on their chemical coding pattern, e.g., increase in the number of CART+/GAL+ nerve fibers." (PMID 30373200, 2018).